USP5 (ubiquitin specific peptidase 5)
Diseases named in the same sentence as USP5 in open-access papers (continued):
Sharing a sentence is not in itself a finding about the gene and the disease.
cancer (continued). "Previous studies demonstrated that although USP5 has a cytoplasmic distribution, its major localization is in the nucleus, where USP5 is involved in regulating the DNA damage repair or heat-induced stress granules in cancer cells." (PMID 37208329, 2023). "Moreover, MBZ can modulate various cancer-associated pathways, including MAPK14, MEK-ERK, C-MYC, USP5/c-Maf, TNIK, XIAP, ELK/SRF, NFKB, MYC/MAX, E2F/DP1, TGF/SMAD, AP1, and STAT1/2, dependent on the specific cancer model." (PMID 36674870, 2023). "As for the role of USP5 in cancer, it has attracted the attention from many researchers recently." (PMID 37268697, 2023). "Finally, we implemented the functional enrichment analysis to recognize the potential mechanisms for USP5 to influence the pathogenesis of cancers." (PMID 37268697, 2023). "This study clarifies the role of USP5 in tumorigenesis from multiple perspectives, providing some bases for further research on the specific mechanisms of USP5 in the progression and treatment of cancers." (PMID 37268697, 2023). "And the immunochemistry results of the Human protein atlas showed that staining intensity of USP5 was greater in many cancers, mainly including BRCA, LIHC, OV, PRAD, READ and UCEC, which was consistent with the analysis result of the mRNA expression level of USP5 from TCGA + GTEx." (PMID 37268697, 2023). "Then we used GEPIA to acquire the top 100 USP5 co-expressed genes in pan-cancer." (PMID 37268697, 2023). "In summary, using comprehensive bioinformatics analysis methods, our study explored the expression levels, potential diagnostic and prognostic value, genetic mutation, protein methylation, immunomodulatory effects and relevant signaling pathways of USP5 in pan-cancer." (PMID 37268697, 2023). "Based on our results, USP5 had a certain diagnostic accuracy (AUC > 0.7) in 20 cancer types, especially in predicting BRCA, CHOL, DLBC, LGG, LUSC, PAAD and THYM (AUC > 0.9), indicating the potential clinical application value of USP5 as a reliable diagnostic biomarker." (PMID 37268697, 2023). "The potential molecular mechanism of USP5 related to tumorigenesis and whether USP5 could be a target for cancer therapy still need more experimental exploration." (PMID 37268697, 2023). "In the present study, using multiple bioinformatics approach, we first revealed the abnormal expression of USP5 in human cancers and its expression level in different molecular and immune subtypes of cancers, then we explored the diagnostic and prognostic values of USP5 in various cancers." (PMID 37268697, 2023). "Using UALCAN database, we compared the methylation level of USP5 between normal and cancer tissues." (PMID 37268697, 2023). "This suggests the molecular mechanisms by which cancer cells develop resistance to USP5 inhibition." (PMID 33919439, 2021). "Thus, we identified that USP5 was a new regulator of PD-L1 and targeting USP5 is a promising strategy for cancer therapy." (PMID 34741014, 2021). "Knockdown of USP5 has been found to inhibit proliferation of various cancer cell lines." (PMID 34948102, 2021). "Therefore, cancer therapy involving cell death targeting through USP5 can evoke unexpected cellular and physiological side effects." (PMID 33919439, 2021). "Therefore, degrasyn holds promise as cancer therapeutic agent in PDAC with high expressions of USP5 and WT1." (PMID 31845546, 2020). "Increasing evidence indicates that USP5 functions as an oncoprotein in a variety of human cancers." (PMID 32477134, 2020). "Recently, there have been several reports on how USP5 promote the growth of cancer." (PMID 33123271, 2020). "This suggests that dependency of cell survival and proliferation on USP5 expression may be cancer cell specific." (PMID 29029505, 2017). "Pharmacological inhibition of USP5 may be a promising strategy for current cancer therapies." (PMID 41321309, 2025).
cancer (continued). "IHC showed that expression levels of both USP5 and EphA2 in the cancer tissues were significantly higher than those in the normal tissues, and USP5 levels were positively correlated with EphA2 levels in cancer tissues, supporting USP5 as the deubiquitinase of EphA2 in NPC." (PMID 39897046, 2025). "In addition, treatment with PYR41, a ubiquitin-activating enzyme E1 inhibitor, and MLN4924, an E3 ligase inhibitor, did not decrease total levels of p-STAT1/2, but markedly reduced the cytosolic p-STAT2 puncta as well as p-STAT1/2 levels in LEVs from USP5-depleted cancer cells." (PMID 41321309, 2025). "Moreover, whether the inhibitory effect of USP5 on ferroptosis of cancer cells is a common phenomenon in pan‐cancer remains to be further explored." (PMID 37492786, 2023). "However, the detailed role of USP5 in pan-cancer remains elusive so far." (PMID 37268697, 2023). "Moreover, the patients with USP5 alteration had shorten progress-free survival in pan-cancer." (PMID 37268697, 2023). "However, the studies on the USP5 gene alteration in human cancers were still rare." (PMID 37268697, 2023). "In addition, we found that there were meaningful correlations between USP5 expression level and the different molecular or immune subtypes of cancers, which suggested to us to get a deeper understanding of USP5’s function in cancer by targeting specific molecular or immune subtypes." (PMID 37268697, 2023). "Additionally, via the functional enrichment analyses of USP5 co-expressed genes, we showed that “spliceosome” and “RNA splicing” may be the critical mechanism for USP5 to involve in pan-cancer." (PMID 37268697, 2023). "Thus, targeting USP5 to reduce autophagy and impose senescence burden may be a potential therapeutic strategy for cancer treatment." (PMID 36528652, 2022). "Moreover, shorter form of USP5 is highly proportional to the PD-L1 protein levels in cancer cells, which indicates shorter form of USP5 might play more important role in regulating PD-L1 stability." (PMID 34741014, 2021). "In addition to intrinsic apoptosis, USP5 suppresses extrinsic apoptosis in cancer cell lines." (PMID 33919439, 2021). "Therefore, USP5 is recognized as an oncogene for promoting tumorigenesis in various of cancers." (PMID 34741014, 2021). "Therefore, upregulation of Usp5 is a frequent event in human HCC, indicating that Usp5 may be involved in malignant tumor development and progression." (PMID 28881591, 2017). "Inhibition of ERK interrupts USP5-mediated PD-1 stability, enhancing the efficacy of anti-PD-1 and anti-CTLA therapy in cancer treatment." (PMID 40238877, 2025). "USP5 stabilized STAT3 via its deubiquitination function, thereby enhancing the production of pro-angiogenic factors by cancer cells, including VEGF, ANGPT2, and CXCL1." (PMID 40691441, 2025). "Taken together with our results showed that knockdown of USP5 significantly inhibited the aerobic glycolysis process, further development of USP5 inhibitors to reverse the aerobic glycolysis of cancer cells and reduce cancer progression may contribute to future clinical treatment of cancer." (PMID 38217030, 2024). "And USP5 could regulate the stability of many tumorigenesis‐associated proteins, such as forkhead box M1 (FoxM1), MAF bZIP transcription factor (c‐Maf), Tu translation elongation factor, mitochondrial, and snail family transcriptional repressor 2 (SNAI2) to promote the cancer progression." (PMID 37492786, 2023). "Meanwhile, activation of ERK phosphorylates METTL3 and stabilizes its expression by increasing USP5-mediated deubiquitylation, resulting in ERK-activated cancer cell tumorigenesis." (PMID 37015927, 2023). "In addition, USP5 may be a potential prognostic and immune-related biomarker for cancer patients." (PMID 37268697, 2023). "Therefore, therapies targeting USP5 may play a positive role in cancer treatment." (PMID 36611139, 2023).
cancer (continued). "G9(+)-mediated inhibition of USP5 abolished acquired TRAIL resistance and enhanced apoptosis in cancer cell lines." (PMID 33919439, 2021). "Therefore, discovery of a new substrate for USP5 may be of great importance for cancer therapy." (PMID 31410188, 2019). "Targeting USP5 might thus offer a new avenue for anti-angiogenic therapies to improve the treatment of ESCC and other cancers where angiogenesis plays a critical role, which is warranted for clinical validation." (PMID 40691441, 2025). "This study reveals a mechanism by which USP5 regulates SLC7A11 independently of the ubiquitin system, expanding the regulatory network of SLC7A11 and further highlighting the heterogeneity of DUB functions in different cancers." (PMID 41213937, 2025). "Through the isolation of large EVs (LEVs) and classical exosomes from culture medium, we found p-STAT1 and p-STAT2 in LEVs, but not in classical exosomes, from USP5-depleted cancer cells after IFN-β treatment." (PMID 41321309, 2025). "The inhibition of USP5’s activity may help to modulate the stability of EMT transcription regulators and, in turn, hinder cancer cell proliferation and EMT, which are crucial steps in cancer progression." (PMID 38248666, 2024). "Importantly, we identified that PFKP was a bona fide target of deubiquitinase USP5, and the USP5-mediated deubiquitination and stabilization of PFKP were essential for cancer cell aerobic glycolysis and TNBC progression." (PMID 38217030, 2024). "Also, we observed that USP5 was correlated with most immune inhibitors and immune stimulators except for KIR2DL1, KIR2DL3 and TNFSF18 in pan-cancer." (PMID 37268697, 2023). "Moreover, we found that USP5 showed certain correlation with majority of chemokines with the exception of CCL1, CCL16, CCL27, CCL24 and CCL25 in pan-cancer." (PMID 37268697, 2023). "As Degrasyn (a selective inhibitor of USP5, USP9X, and USP14) has shown an inhibitory effect on some cancer types, our aim was to determine whether Degrasyn could be a potential therapeutic agent in BC." (PMID 36979739, 2023). "We did not observe any systematic differences in the expression levels of USP5 among cancer cell lines of different origin or between the cancer cells and the non-transformed cell-line HEK293." (PMID 29029505, 2017). "Additionally, although DUB inhibitors have shown promise in cancer therapy, no specific USP5‐targeting drugs are currently available." (PMID 40066708, 2025). "In addition, USP5 has been reported to stabilize glycolytic enzymes such as PFKFB4 and PFKP in cancer, raising the possibility that similar mechanisms may exist in RA." (PMID 41339332, 2025). "However, the diverse biological significance of USP5 in pan-cancer has not been systematically and comprehensively studied." (PMID 37268697, 2023). "Meanwhile, a negative correlation between USP5 and most chemokine receptors could be found in the majority of malignant tumors especially in ESCA, KICH, LUSC and TGCT." (PMID 37268697, 2023). "Last, we studied the effect of USP5 genetic alteration on the prognosis of patients in pan-cancer, and the result indicated that patients with USP5 alteration had poor progress-free survival in pan-cancer, but not overall survival, disease-free survival and disease-specific survival." (PMID 37268697, 2023). "Thus, therapies that target USP5 activity may diminish TRAIL resistance and enhance the therapeutic efficacy of TRAIL-targeted therapies in human cancers." (PMID 31645897, 2019). "STAT2 depletion in USP5-deficient cancer cells significantly reduced upregulated CXCL9 and CXCL10 mRNA, as well as CD86 and HLA-DR protein of cocultured THP1-MΦ; these reductions were rescued by restoring WT-STAT2 but not the Y690A mutant in USP5-depleted cells." (PMID 41321309, 2025). "Moreover, the knockdown of USP5 significantly reduced TNBC progression through the regulation of PFKP, suggesting that USP5 may serve as a potential therapeutic target for patients with cancer." (PMID 38217030, 2024).
cancer (continued). "However, the significance of USP5 in pan-cancer has not been explored until now." (PMID 37268697, 2023). "We cannot exclude “off target” anti-cancer effects of the combination therapy which do not involve MYCN and USP5." (PMID 33658627, 2021). "Several USP5 inhibitors have been proposed for human cancers, such as PYR-41, formononetin, and WP1130 or one of its optimized analogues EOAI3402143 (G9), but these compounds do not exclusively target USP5." (PMID 35884430, 2022).
infection (4 papers, 2015 to 2025). The state of being infected such as from the introduction of a foreign agent such as serum, vaccine, antigenic substance or organism. "Meanwhile, there were less cells at S phase and G2/M phase after USP5 shRNA#1 and #2 infection, compared with control cells and NC infected cells (P<0.001)." (PMID 31727867, 2019). "Following infection with SeV-GFP and VSV-GFP, we observed fewer virus-infected cells in the USP5-/- cells compared to the WT cells." (PMID 39761299, 2025). "We identified new chicken DUBs on the basis of the reaction with the Ub-VS probe and characterized USP4, USP5, UCH-L3 and UCH-L5 as DUBs regulated in infection." (PMID 26267804, 2015). "The blocking activity of WP1130 is restricted to five DUBs; however, two of these enzymes, USP5 and UCHL5, are also targets of PR-619, which did not affect productive infection." (PMID 36851696, 2023).
colorectal (2 papers, 2025). "Furthermore, colony formation assays revealed that USP5 overexpression significantly increased proliferative capacity in CRC cells, confirming its pro-tumorigenic function in colorectal carcinogenesis." (PMID 41213937, 2025).
neurodegenerative disease (2 papers, 2022 to 2025). A disorder of the central nervous system characterized by gradual and progressive loss of neural tissue and neurologic function. "It is worth noting that the functional studies of USP5 are rapidly expanding, with its regulatory network involving DNA repair, inflammation, tumorigenesis, neurodegenerative diseases, and other areas." (PMID 41213937, 2025).
USP5 also shares sentences with these, for which no sentence is quoted: multiple myeloma (6 papers); nasopharyngeal carcinoma (2); pancreatic ductal adenocarcinoma (2); acute lymphoblastic leukemia (1); chronic pancreatitis (1); clear cell renal cell carcinoma (1); colon adenocarcinoma (1); esophageal cancer (1); gastrointestinal stromal tumor (1); head and neck squamous cell carcinoma (1); intrahepatic cholangiocarcinoma (1); malignant peripheral nerve sheath tumor (1); myeloproliferative neoplasm (1); nonalcoholic fatty liver disease (1); Pain (1); plasma cell leukemia (1); postherpetic neuralgia (1); prostate carcinoma (1); proteinopathies (1); rectum adenocarcinoma (1); skin cancer (1); smoldering myelomas (1); triple-negative breast carcinoma (1); type II diabetes (1); uveal melanoma (1).